IL2 (interleukin 2)
Diseases named in the same sentence as IL2 in open-access papers (continued):
Sharing a sentence is not in itself a finding about the gene and the disease.
cognitive decline (continued). "-MaR1 improved cognitive decline by reducing pro-inflammatory cytokines (TNF-α, IL-6, MCP-1) and increasing anti-inflammatory cytokines (IL-2, IL-10) levels." (PMID 39452854, 2024). "AD patients with intermediate cognitive decline showed significantly higher levels of IL-2 (p = 0.021), IL-4 (p = 0.016), IFN-γ (p = 0.018) and PDGF (p = 0.031) compared to those with slow cognitive decline over one year." (PMID 23762274, 2013). "Potential response to an IL2‐based therapy will likely vary, as illustrated, for example, by the data shown here on protection from cognitive decline in a pure age‐based model but not in a model driven by amyloid plaque formation." (PMID 36975362, 2023). "The aMCI group showed that higher baseline levels of IL-2 (r = 0.420, p = 0.041), sCD40L (r = 0.419, p = 0.041), IL-8 (r = 0.410, p = 0.047), and VEGF (r = 0.491, p = 0.017) were significantly correlated with a lower cognitive decline." (PMID 34122046, 2021). "However, evidence that multiple serum and CSF proinflammatory cytokines and chemokines, including IL-2, IL-1β, IL-6, IL-10 and IFN-γ, decline over time and may be undetectable in AD suggests that related topic study outcomes can vary with disease stage and cognitive decline." (PMID 37760836, 2023).
endothelial dysfunction (16 papers, 2017 to 2025). In vascular diseases, endothelial dysfunction is a systemic pathological state of the endothelium (the inner lining of blood vessels) and can be broadly defined as an imbalance between vasodilating and vasoconstricting substances produced by (or acting on) the endothelium. "IL-2 immunotherapy causes endothelial dysfunction, eventually inducing VLS." (PMID 37711172, 2023). "Superantigens bypass normal antigen presentation by linking MHC class II molecules with T-cell receptors, causing massive cytokine release (IL-1, IL-2, TNF-α, IL-6, and IFN-γ), endothelial dysfunction, and multiorgan injury." (PMID 41294916, 2025). "Increased ADMA levels and their relationship with poor EFR and increased IL-2 might suggest the existence of an early endothelial dysfunction in young adults with AP." (PMID 39077523, 2023). "Similarly, HTP use was associated with increased IL-8, IL-6, and IL-2 levels (p < 0.05), as well as higher white blood cell (WBC), leukocyte (p < 0.05), and eosinophil levels (p < 0.01), and an increase in the inflammatory response (p < 0.01), followed by endothelial dysfunction." (PMID 40868658, 2025). "Interleukin-2 (IL-2) has been recently proposed as a predictor of HFpEF development, playing a hypothesized role in chronic microvascular inflammation, while neutrophilic myeloperoxidase (MPO)-related oxidative stress has been associated with endothelial dysfunction in HFpEF." (PMID 39062871, 2024). "In aged mice, the systemic inflammatory response (serum amyloid A, IL-1β, IL-2, eotaxin), kidney injury (urea), liver injury (ALT), and endothelial dysfunction induced by a relatively low dose of LPS (3 mg/kg) were all more pronounced as compared with young mice." (PMID 41291381, 2025). "Based on the current findings, IL-1RA, IL-2, IL-4, IL-6, GM-CSF and IFN-γ were elevated to remarkably high levels in DM-SFTS patients, likely contributing to the fatal outcome, together with the development of depressed immunity and endothelial dysfunction." (PMID 31136581, 2019). "Many cytokines such as TNF-alpha, IL-1, IL-2, IL-4, IL-6, IL-18, monocyte chemoattractant protein-1 (MCP-1), vimentin, and platelet-derived growth factor (PDGF) are produced by macrophages and T lymphocytes activated due to endothelial dysfunction and oxidative stress." (PMID 34349888, 2021). "Moreover, IL-2 reduced mt ROS from HUVECs exposed to sera from RUPP rats, indicating that IL-2 was able suppress circulating factors produced in response to placental ischemia that stimulate endothelial dysfunction." (PMID 34685775, 2021).
fungal infection (16 papers, 2012 to 2025). "Therefore, correcting the imbalance of IL-2 and IL-4 caused by fungal infection may contribute to the restoration of local immune homeostasis." (PMID 35295335, 2022). "Th1-associated cytokines, such as IL-1β, IL-2, IFN-γ, and TNF-α, play crucial roles in macrophage recruitment, activation, and the generation of reactive oxygen species to combat fungal infections while promoting CD4+ T-cell responses." (PMID 41425969, 2025). "Further, a significant variation in IL-17A, TNF-β, IL-1β, IL-2, IL-4, IL-6, IL-8, IL-10, IL-22, and IL-12p70, between the uninfected group and the pulmonary bacterial and fungal infection group (P < 0.05) was observed." (PMID 36319826, 2022). "Our results show that only IL-2 was significantly upregulated in the patients with fungal infection compared to the bacteria-infected patients." (PMID 34684298, 2021). "During fungal infection, Th1 cells secrete pro-inflammatory cytokines such as IL-2, IL-12, IL-18, and IFN-γ which stimulates phagocytic activity, cytotoxic CD4+ T cell generation, and prevents the hypersensitivity reaction." (PMID 32801570, 2020). "Therefore, in fungal infection low concentrations of IL-2 correlate with upregulated levels of Th2 cytokine secretion." (PMID 32801570, 2020). "Our results showed that the IL-2 levels in the rabbits of the FI group were significantly higher than that of the control group 2 days after fungal challenge, indicating that T cells play a role against fungal infection in this animal model." (PMID 31579583, 2019). "Additionally, we found increased IL-2 expression in lesional skin and in PBMCs exposed to S. globosa in vitro, and blocking IL-2 with its antibody further decreased Th2 induction, indicating that IL-2 indeed participates in driving Th2 response with IL-18 in this fungal infection." (PMID 40489556, 2025). "There were significant differences in IL-4, IL-6, IL-8, IL-10, IL-12p70, IL-1β, IL-2, TNF-β, IL-17, and IL-22 between the uninfected group and the pulmonary bacterial and fungal infection group (P < 0.05)." (PMID 36319826, 2022). "Since, we have previously shown that A. fumigatus swollen conidia, more than ungerminated conidia, induces Ca2+/NFAT/IL-2 pathway in DCs, here we went to study the regulation of LRRK2 in response to fungal infection." (PMID 29472933, 2018). "Since, the Ca2+/NFAT/IL-2 axis has been previously found to regulate DC response to the fungus Aspergillus, we have investigated the role played by the kinase LRRK2 during fungal infection." (PMID 29472933, 2018). "Fungal infections inducing the Th-1 cytokines (e.g. IFN-γ, TNF-α, and IL-2) in the serum of infected individuals have been reported and these are involved in macrophage activation, nitric oxide production, and cytotoxic T lymphocytes proliferation to enhance phagocytosis and fungal clearance." (PMID 38787374, 2024). "When a pathogen was detected, it was more commonly viral (N=86 in total; 47 in the ATG and 39 in the IL-2 RA group) or bacterial (N=91 in total; 52 in the ATG and 39 in the IL-2 RA group), with some instances of fungal infections (N=10 in total; 4 in the ATG and 6 in the IL-2 RA group)." (PMID 39606231, 2024). "Hence, cortisol plays an important role during fungal infection through its ability to suppress the host immune system by downregulating TNF-α, IFN-γ, and IL-2 cytokines." (PMID 32801570, 2020). "C. albicans gDNA uniquely promotes Treg induction while preserving CD4+ T cell viability in an inflammatory milieu (IL-2 + TGF-β stimulation) or in splenocytes, suggesting that its DNA may help counterbalance T cell exhaustion and inflammation induced by fungal infection." (PMID 41295141, 2025).
acute kidney injury (15 papers, 2008 to 2025). Sudden and sustained deterioration of the kidney function characterized by decreased glomerular filtration rate, increased serum creatinine or oliguria. "Despite the potential of IL-2, the use of high-dose IL-2 is limited due to severe associated toxicities, such as hypotension, pulmonary edema, and renal failure, which restrict its broader clinical use." (PMID 37516849, 2023). "Anotherexample of selection bias occurs with induction therapy, correlates with IL-2 receptorantagonists, and a risk of renal dysfunction, and this medication is indicated forpatients at high risk for renal failure after transplantation." (PMID 26107815, 2015). "High-dose IL-2 created a septic shock-type reaction with hypotension, hypoxemia, and acute renal failure necessitating an intensive care unit (ICU) level of support while receiving the treatments." (PMID 40718227, 2025). "Ori has been shown to ameliorate acute kidney injury by inhibiting macrophages-mediated inflammation, and suppressing the expression of cytokines IL-2, IL-4, IL-6, IL-10, and TNF-α, suggesting that Ori had a potent anti-inflammatory response activity." (PMID 37375489, 2023). "Of the other two patients who only received four doses of IL-2, one developed grade 3 edema, and the other developed grade 2 edema and grade 1 renal failure that resolved with the discontinuation of IL-2." (PMID 30747243, 2019). "Recently, we demonstrated a role for IL-33 in promoting Treg responses, such that IL-2 and IL-33 can synergize to increase Tregs and protect from experimental acute kidney injury." (PMID 31191312, 2019). "G. vaginalis-exposed mice displayed higher levels of IL-1α, IL-1β, TNF-α, MIP-1β, and IL-2 in the kidney and higher levels of serum creatinine, a biomarker of acute kidney injury, than PBS controls." (PMID 28358889, 2017). "In addition, cytokines, such as TNF, IL-2, or IL-6, contribute to acute kidney injury and renal failure, as reported in critically ill COVID-19 patients." (PMID 36235704, 2022). "Further analysis demonstrated thatthe combination of TNF-α, interleukin 2, interleukin 6, and NGAL hadthe highest predictive value for acute kidney injury (area under the curve =0.93)." (PMID 40961276, 2025). "Mice with normal numbers of NKT cells had higher levels of cytokine early after treatment IL-2, IL-4, IFN-γ, and IL-17 in mouse kidney with subsequent renal failure as well as urine abnormality." (PMID 25904903, 2015).
glaucoma (15 papers, 2012 to 2023). Increased pressure in the eyeball due to obstruction of the outflow of aqueous humor. "As shown in the analysis, there is a major association with Th1-cytokines in the case of glaucoma only (IL2, IL12), and a minor association with keratitis (IL2) and scleritis (IL1β)." (PMID 31810226, 2019). "WD36 is co-regulated with T-cell growth factor IL-2 and has been linked to glaucoma." (PMID 24910846, 2014). "In the iris of glaucoma patients, expression of Th1 cytokines (IL-2 and IFN-γ) increased, Th2 cytokine IL-6 decreased, and TGF-β increased." (PMID 25811482, 2015). "Levels of IL-2 or IL-4 in glaucoma patients are controversial in previous studies." (PMID 37020269, 2023). "We did not observe any SNPs in the IL-2 genes as being associated with glaucoma in POAAGG cohort." (PMID 35052396, 2021). "In summary, our study showed that the expression levels of TNF-α, IL-2, IL-6, IL-8, BDNF, MMP-2, MCP-1, VEGF, IFN-γ, LT-α, bFGF, PDGF-AA, and TIMP-1 were different among the 3 types of glaucoma." (PMID 36254076, 2022). "Numerous other pro-inflammatory cytokines (and chemokines) known to be NF-κB’s target genes, such as IFN-γ, IL-1, IL-2, IL-12, IL17, or iNOS, also exhibit astroglial upregulation during neurodegeneration in glaucoma." (PMID 32859212, 2020). "Consistent with the real-time PCR results, expression levels of IL-2, IFN-γ, and TGF-β in the iris of glaucoma patients increased or showed an upward trend." (PMID 25811482, 2015). "Therefore, we simultaneously compared serum and aqueous levels of TNF-α, IL-2, TGF-β2 and IL-4 and investigated the possible effects of cytokine levels on clinical characteristics and postoperative outcomes in glaucoma patients." (PMID 37020269, 2023). "In the DBA2J mice, an experimental glaucoma model that developed PAS at 50 weeks, the AqH levels of IL-2, IL-6, IL-10, IFN-γ, tumor necrosis factor-α, MCP-1 and granulocyte-macrophage colony-stimulating factor (GM-CSF) significantly increased at 50 weeks compared to 8 weeks (p ≤ 0.021)." (PMID 34830147, 2021). "Quantifying IL-2 and TNF-α in glaucoma patients may additionally help monitor disease progression and the efficacy of therapy." (PMID 35052396, 2021). "Ten’s research showed that the expression of IL-2, IL-6, monocyte chemoattractant protein-1 (MCP-1), and placental growth factor (PlGF) were significantly up-regulated in the intraocular fluid of RP patients, and the level of IL-8 was higher in presence of glaucoma." (PMID 34399712, 2021).
Hyperglycemia (15 papers, 2009 to 2024). An increased concentration of glucose in the blood. "Furthermore, acute and acute-on-chronic hyperglycaemia had unique associations with the inflammatory pathways involving GM-CSF and IL-2, respectively." (PMID 38840922, 2024). "Immunomodulation:- ↑ Phagocytic activity of blood monocytes and neutrophils.- ↑ IL-2 and anti-ovalbumin antibodies production (antibody response).- ↓ Blood glucose in dogs with hyperglycemia." (PMID 37954670, 2023). "Three days after onset of hyperglycemia, the numbers and size of islets appeared similar between controls and Ab/IL-2-treated mice." (PMID 24205242, 2013). "In our study, the safety profile of EMD 273063 was consistent with the expected IL2 side effect profile as reported in the previous phase I clinical trial, except for a lower incidence of hyperglycemia and hypophosphatemia." (PMID 19640287, 2009). "IL-2 is central in adaptive immune responses and immune tolerance, hence alterations of its levels by hyperglycemia may have adverse health implications." (PMID 39981106, 2024). "Moreover, the development of hyperglycemia in C57BL/6 mice after streptozotocin administration coincides with a decrease in IL-2+ ILC3 and Treg numbers in SILP." (PMID 37110604, 2023). "In overtly diabetic mice, IL-2 monotherapy was not sufficient for hyperglycemia reversal, however, IL-2 combined with sirolimus (rapamycin/RAPA) was even associated with a deleterious effect on pancreatic beta cells." (PMID 25322151, 2014). "Furthermore, all but one of the anti-IL-2 treated mice that showed hyperglycemia developed a milder form of disease remaining alive until the end of the experiment." (PMID 20856822, 2010). "Moreover, it has been suggested that hyperglycemia may decrease cytokine production, such as IL-2, IL-6, and IL-10, impair leukocyte function, and impair leukocyte defense against infection." (PMID 39744260, 2024). "The evidence showed hyperglycemia to be associated with unfavorable treatment outcomes; altered counts and functioning of dendritic cells, monocytes, and CD4+ T cells; and changes in cytokine levels (mainly INF-γ, IL-17, IL-1β, IL-2, IL-6, IL-10, and TNF-α) in patients with DM-TB." (PMID 39981106, 2024). "Therefore, changes in each homeostatic cytokine pathway, namely IL-2 and IL-15, may result in more profound desirable alteration in Treg/Teff cells, manifesting as permanent reversal of hyperglycemia in NOD mice." (PMID 25322151, 2014). "Chronic hyperglycemia rather than acute hyperglycemia is important in inducing inflammation in the lungs through cytokines such as IL-2, IL-17, and TNF-α (Ngo, Bartlett and Ronacher, 2021)." (PMID 39981106, 2024). "Low dose IL-2, on the other hand, protected half of the STZ mice from developing hyperglycemia." (PMID 38424350, 2024). "The levels of IL-1β and IL-2 were not affected by different glucose concentrations, and the differences for these cytokines in hypo-, normo-, and hyperglycemia were not statistically significant." (PMID 38542084, 2024). "To determine whether the same correlation between the presence of IL-2+ ILC3 and Treg within the SILP exists in another model of T1D, we chemically induced insulitis and subsequent hyperglycemia in C57BL/6 mice using MLDS." (PMID 37110604, 2023). "This was true for hypo-, normo-, and hyperglycemia, with a few exceptions: there was a lack of statistical significance between observed differences for IL-1α, IL-2 and IL-4 in the hypoglycemic environment and non-significant differences for IL-2 in hyperglycemia." (PMID 38542084, 2024). "Furthermore, low-dose IL-2 dampened cytotoxic activity of pancreas infiltrating CD8+ T cells, thus providing protection from chronic inflammation and, consequently, reversed hyperglycemia." (PMID 25322151, 2014).
malnutrition (15 papers, 2008 to 2025). Inadequate nutrition resulting from poor diet, malabsorption, or abnormal nutrient distribution. "HF patients often experience malnutrition and inflammatory complications, which lead to increased release of interleukin-2 and interleukin-6." (PMID 39659906, 2024). "Due to a decrease in activated CD4+ T cells, the effect of malnutrition on IL-2 production, as IL-2 is important for T cell proliferation was determined." (PMID 32033605, 2020). "Furthermore, beyond disrupting metabolic and endocrine functions in diabetic patients, malnutrition also profoundly modifies immune-related cytokine expression, including interleukin-2 (IL-2), interleukin-8 (IL-8), and interleukin-21 (IL-21)." (PMID 40977986, 2025). "low concentrations of INF-γ, IL-2 and IL-12 coupled either with high concentrations of IL-10 or, at least, with levels of this cytokine that were apparently unaffected despite catabolic malnutrition." (PMID 38068780, 2023). "Therefore, in patients with malnutrition, decreased antigen‐presenting ability, and decreased interleukin (IL)‐2 and interferon (IFN)‐γ production may be observed, leading to decreased activation and migration CD8+ lymphocytes." (PMID 36091309, 2022). "DM often results in the poor condition of malnutrition, which will lower the immune status by decreasing the lymphocytes production, IFN-gamma and IL-2 level, and increasing the levels of TGF-beta." (PMID 35332512, 2022). "By contrast, blood cytokine levels were largely unaffected except that, regardless of the form of malnutrition, high blood concentrations of three type 1 cytokines (IL-2, IL-6 and TNF-α) proved independently predictive of inpatient mortality." (PMID 38068780, 2023). "With reduced effector T cell numbers and low IL-2, it is possible that malnutrition affect proliferation as well, but this was not tested in this current study." (PMID 32033605, 2020). "Cytokines commonly found to be low in malnourished children included IL- 1 and IL-2, although one study found both cytokines to be normal in non-oedematous malnutrition and lower in oedematous malnutrition." (PMID 25153531, 2014). "Malnutrition promotes the phenotypic transformation of immune cells to pro-inflammatory phenotypes, secreting pro-inflammatory cytokines such as IL-1β, IL-6, IL-8, TNF-α, and IL-2, while anti-inflammatory cytokines such as IL-1 receptor antagonists, IL-4, IL-10, and IL-13 decrease." (PMID 35003070, 2021).